MPO (myeloperoxidase)
Diseases named in the same sentence as MPO in open-access papers (continued):
Sharing a sentence is not in itself a finding about the gene and the disease.
cardiovascular disease (146 papers, 2006 to 2025). "Diabetic dyslipidemia is a known risk factor for PAD, and in T2DM nitrated lipoproteins, modified lipoproteins produced by the nitration of the tyrosyl residues of apolipoproteins by myeloperoxidase are also linked with cardiovascular disease." (PMID 38397984, 2024). "As a cardiac biomarker, MPO is significant due to its association with inflammation and oxidative stress, both of which are pivotal in the development and progression of cardiovascular diseases." (PMID 39273041, 2024). "Accordingly, MPO gene-deficiency and inhibition has been reported to protect against atherosclerotic plaque instability and MI in pre-clinical models of cardiovascular disease." (PMID 39061857, 2024). "Myeloperoxidase (MPO), a neutrophil-derived heme enzyme, is gaining increased attention owing to its association with various cardiovascular diseases." (PMID 37719981, 2023). "Considerable data indicates that high levels of MPO, and its oxidants are associated with tissue damage in both cardiovascular diseases and other inflammatory pathologies." (PMID 36829979, 2023). "The results of new biomarkers of cardiovascular disease risk showed differences in the myeloperoxidase level (MPO), which was significantly higher in both diabetic groups compared to the healthy controls." (PMID 36012972, 2022). "An elevated myeloperoxidase level is associated with increased risk, prevalence, and severity, and predicts a poor prognosis in patients with cardiovascular disease." (PMID 36142645, 2022). "MPO is linked to many aspects of human cardiovascular disease and it is believed that this enzyme acts on both the initiation and propagation of cardiac pathologies." (PMID 36142645, 2022). "Several studies have found a strong association between cardiovascular diseases and myeloperoxidase (MPO) as a marker of oxidative stress." (PMID 35983482, 2022). "Many studies suggest that the enhanced level of MPO is one of the best diagnostic tools of inflammatory and oxidative stress biomarkers for cardiovascular disease." (PMID 34440245, 2021). "Association of myeloperoxidase (MPO) with HDL has been implicated in the loss of PON1 activity in cardiovascular diseases." (PMID 34331945, 2021). "Several types of tissue injuries and chronic diseases, including cardiovascular diseases, are associated with MPO-derived oxidants." (PMID 34440245, 2021). "Nevertheless, MPO deficiency is beneficial in various inflammatory diseases, such as cardiovascular disease, neuronal disease, pulmonary and renal inflammation." (PMID 33391487, 2021). "Excess MPO impairs phagocytic function and triggers neutrophil degranulation, causing inflammatory tissue damage in cardiovascular disease." (PMID 33224136, 2020). "Excessive production of hypohalous acids has been shown to be directly linked to many cardiovascular diseases and circulating levels of MPO is clinically used as a biomarker to predict the health outcomes in those patients." (PMID 32536875, 2020). "Prospective studies showed that high MPO levels predict increased risk of cardiovascular disease in healthy individuals." (PMID 29214330, 2018). "Several epidemiological studies have shown a positive association between concentrations of plasma MPO and cardiovascular disease (CVD)." (PMID 30300402, 2018). "Increased MPO levels have been found to be associated with complex and calcified atherosclerotic lesions and incident cardiovascular disease." (PMID 29333213, 2017). "Myeloperoxidase (MPO) is a circulating cardiovascular disease (CVD) biomarker used to estimate clinical risk and patient prognosis." (PMID 25666092, 2015). "Elevated levels of MPO in humans correspond to increased risk of cardiovascular disease, while human MPO deficiency is cardioprotective." (PMID 26491535, 2015). "Other studies have shown that serum MPO levels can predict incident risk of cardiovascular disease and death in healthy middle-aged and elderly subjects." (PMID 23637811, 2013).
cardiovascular disease (continued). "Because MPO is regarded as an important risk factor for cardiovascular diseases associated with increased platelet activity, we studied the effects of MPO on human platelet functional properties." (PMID 24143278, 2013). "Active MPO can be demonstrated in extracts from human atherosclerotic arteries, circulating MPO levels independently predict the risk to develop events of cardiovascular diseases and −463 MPO polymorphism predicts the risk for cardiovascular events." (PMID 23874490, 2013). "Clinical studies have shown that patients with MPO-deficiency or low blood levels of MPO have reduced risk of cardiovascular disease." (PMID 22723891, 2012). "In addition, polymorphisms in the promoter of the MPO gene and coding regions have been reported to be associated with cardiovascular disease." (PMID 39456241, 2024). "Increased plasma MPO levels are associated with cardiovascular disease." (PMID 38736886, 2024). "Elevated MPO levels are associated with a poor prognosis and a high risk of cardiovascular disease." (PMID 36551214, 2022). "Both urate and MPO are associated with adverse outcomes in cardiovascular disorders." (PMID 36116160, 2022). "Elevated MPO levels have been associated with cardiovascular disease." (PMID 35326206, 2022). "This suggests previous associations between MPO genetic scores and cardiovascular disease may have been driven by variants in these highly pleiotropic regions." (PMID 35504531, 2022). "Elevated MPO usually indicates a high risk of cardiovascular disease and a poor prognosis." (PMID 34859069, 2021). "While more studies are needed, MPO-ANCA+ patients may be at higher risk for death due to cardiovascular disease even after accounting for differences in renal involvement, age, and sex." (PMID 31867013, 2019). "Our study suggests that in addition to mature MPO, circulating pro-MPO may cause oxidative modifications of proteins thereby contributing to cardiovascular disease." (PMID 29590135, 2018). "Elevated levels of MPO have been linked with inflammation and with cardiovascular diseases." (PMID 30139351, 2018). "MPO has already been developed as a diagnostic tool for cardiovascular disease risk stratification." (PMID 29181450, 2017). "It should be noted that in clinical studies, protein-bound homocitrulline levels predicted cardiovascular disease even after extensive adjustments for traditional cardiovascular risk factors, renal function, and both MPO levels and high sensitivity C-reactive protein concentrations." (PMID 29333213, 2017). "MPO plays a significant role in the development of the atherosclerotic lesion and renders the plaques unstable, which is associated with the aging mechanism and cardiovascular disease." (PMID 26064421, 2015). "Inflammatory monocytes express MPO and are implicated in cardiovascular disease." (PMID 25066128, 2014). "In the past few years, evidences emerging from epidemiological studies have shown that higher concentrations of MPO are associated with an increased risk for cardiovascular disease, in the initiation and progression of which platelets are thought to play a predominant role." (PMID 24143278, 2013). "Importantly, several studies have furthermore implicated a role for MPO in human cardiovascular diseases." (PMID 23874490, 2013). "MPO has been associated with cardiovascular disease in many studies." (PMID 21188207, 2010). "Interestingly, it has been shown that sleep deprivation, which is known to correlate with an increase in MPO plasma levels and the risk of cardiovascular diseases, may aggravate numerous psychiatric disorders." (PMID 39201490, 2024). "However, MPO is also associated with oxidative stress and tissue damage resulting from the potent oxidant HOCl, which plays a key pathogenic event in a variety of inflammatory states, including cardiovascular disease." (PMID 33680285, 2021).
cardiovascular disease (continued). "Elevated concentrations of MPO and H3cit in SLE were associated with the presence of concomitant cardiovascular diseases." (PMID 41465552, 2025). "IL-1β and MPO are known biomarkers of atherosclerotic inflammation and contribute to cardiovascular disease (CVD) progression." (PMID 40862746, 2025). "NET components such as dsDNA, MPO-DNA complexes, and citrullinated histones have emerged as significant biomarkers for assessing disease severity and predicting clinical outcomes in cardiovascular diseases." (PMID 40786884, 2025). "Its antioxidant activity also includes the reversible inhibition of myeloperoxidase, an enzyme that promotes oxidative stress and inflammation, leading to cardiovascular disease complications." (PMID 39594991, 2024). "While most of the focus on haem peroxidase enzymes in cardiovascular disease has been on MPO, mounting evidence indicates that another family member, peroxidasin, can also impact disease progression and severity." (PMID 39061857, 2024). "Two studies found that males with cardiovascular disease had increased MPO plasma levels compared to their female counterparts." (PMID 39456241, 2024). "The oxidative mechanisms by which MPO can exacerbate cardiovascular disease are discussed in more detail below." (PMID 39061857, 2024). "Myeloperoxidase (MPO) plays an important role in the immune response of human neutrophils and has been implicated in autoimmune conditions, cardiovascular disorders, and neurodegeneration." (PMID 39533026, 2024). "In the same study, myeloperoxidase levels were higher in healthy dogs than in dogs with a cardiac disease, which contrasts with the trends observed in humans with cardiovascular diseases." (PMID 37035819, 2023). "Considerable data links high levels of MPO, and its oxidants with cardiovascular diseases and other inflammatory pathologies." (PMID 36829979, 2023). "In cardiovascular disease, MPO oxidizes low density lipoproteins, promoting the formation of atherosclerotic lesions and potentially contributing to plaque rupture." (PMID 36293108, 2022). "Most previous studies reported that myeloperoxidase is considered to play a very important role in the initiation and onset of cardiovascular disease, including by increasing LDL, oxidation and accelerating atherogenesis." (PMID 36012972, 2022). "ApoA-I is a selective target for myeloperoxidase-catalyzed oxidation and functional impairment in individuals with cardiovascular disease." (PMID 35326206, 2022). "In order to detect neutrophil activation and NET formation in cardiovascular disease, plasma samples of the three groups were further investigated for MPO, citH3 and circulating cfDNA." (PMID 35203427, 2022). "In line with the efficient transcytosis of MPO through endothelial cells, MPO-derived oxidants are enriched in endothelial and sub-endothelial compartments of vessels of patients with cardiovascular disease." (PMID 35326206, 2022). "The uncontrolled release of MPO promotes inflammation, oxidative stress and cardiovascular diseases." (PMID 36404308, 2022). "MPO is considered a biomarker for various chronic inflammatory diseases, including cardiovascular disease and rheumatoid arthritis." (PMID 35624738, 2022). "Due to the various pathophysiological effects of MPO on cardiovascular disease, pharmacological inhibition has come into scientific focus as a potential therapeutic option." (PMID 36670895, 2022). "Numerous studies, including works from our group, suggest that inhibition of MPO activity is beneficial for the treatment of cardiovascular diseases." (PMID 33916434, 2021). "MPO expression and its enzymatic activity in the blood vessel seem to be detrimental for the progression of cardiovascular diseases." (PMID 33916434, 2021). "This study provides an explanatory framework for the detrimental effects of HOCl-LDL compared to native LDL and cardiac remodeling in patients with high MPO levels during the progression of cardiovascular disease." (PMID 35052529, 2021).
cardiovascular disease (continued). "Currently, the main impact of myeloperoxidase on cardiovascular diseases is related to derivatives of its enzymatic activity." (PMID 33916434, 2021). "In cardiovascular diseases and many other disease scenarios, active MPO and MPO-modified targets are present in atherosclerotic lesions and other disease-specific locations." (PMID 33137905, 2020). "Overwhelming evidence has connected MPO derived oxidants to the pathogenesis of cardiovascular diseases, making MPO a desirable target in therapeutic interventions involving the heart." (PMID 32546914, 2019). "Myeloperoxidase is an emerging therapeutic target in the development of new treatments for inflammation‐related cardiovascular diseases." (PMID 30618054, 2019). "Myeloperoxidase activity can contribute to impaired vascular endothelial function and fibrosis in chronic inflammation‐related cardiovascular disease." (PMID 30618054, 2019). "Myeloperoxidase inhibitors hold therapeutic potential as novel treatments for patients with cardiovascular diseases." (PMID 30618054, 2019). "Myeloperoxidase (MPO)-derived oxidants have emerged as a key contributor to tissue damage in inflammatory conditions such as cardiovascular disease." (PMID 29590135, 2018). "Elevated levels of circulating MPO have been found in patients diagnosed with cardiovascular disease (CVD)." (PMID 29214330, 2018). "In this study, we confirm that pro-MPO is present plasma and elevated in cardiovascular disease patients using a combination of immunoblot analysis and LC-MS/MS." (PMID 29590135, 2018). "Epidemiological studies have reported greater plasma MPO concentration to be associated with increased incidence of several cardiovascular diseases (CVD), but the association of intracellular monocyte MPO (mMPO) with CVD is unclear." (PMID 30300402, 2018). "Our study shows that a precursor of MPO, pro-MPO, is present in circulation and elevated in patients with cardiovascular disease." (PMID 29590135, 2018). "MPO-catalyzed reactions are thought to be involved in all stages of cardiovascular disease, from the initial development of endothelial dysfunction through to the advancement of a mature atherosclerotic plaque and finally its rupture." (PMID 29590135, 2018). "Our data further shows that circulating pro-MPO, like MPO, is elevated in patients with cardiovascular disease." (PMID 29590135, 2018). "Levels of the enzyme myeloperoxidase in the blood are considered a biomarker for the severity of cardiovascular disease." (PMID 25666092, 2015). "An oxidative way of UA degradation concerning myeloperoxidase and hydrogen peroxide has been described in the case of cardiovascular disease and PAR has been found to inhibit this enzymatic system." (PMID 24967235, 2013). "The pathophysiologic role of MPO in cardiovascular disease has attracted considerable interest in the development of MPO inhibitors for therapeutic use." (PMID 23251382, 2012). "The enzyme MPO can convert NO into nitrating oxidants, which are potential inflammatory mediators in cardiovascular diseases." (PMID 21234421, 2010). "Additionally, oxidatively modified HMGB1, along with ROS and myeloperoxidase (MPO) released by neutrophils, can promote the formation and rupture of atherosclerotic plaques, thereby accelerating the progression of cardiovascular disease." (PMID 40877572, 2025). "As such, MPO has long been recognized as a marker in cardiovascular diseases." (PMID 36982778, 2023). "The lack of MPO expression was shown to significantly reduce the risk of cardiovascular disease at the beginning of this century, and subsequent studies have pointed out that MPO gene polymorphisms are associated with an increased risk of CAD." (PMID 37405052, 2023). "In addition, myeloperoxidase (MPO), as a marker of neutrophil activation in cardiovascular disease, endothelial cell apoptosis, and matrix metalloproteases, was directly related to miR-133a levels." (PMID 37559103, 2023).
cardiovascular disease (continued). "The inhibition of myeloperoxidase and collagenase enzymes, which have a role in skin regeneration, wound healing, cardiovascular diseases, inflammatory diseases, neurodegenerative diseases, kidney diseases and immune-mediated diseases, is very important for developing and discovering new drugs." (PMID 36985734, 2023). "The involvement of MPO in cardiovascular diseases is often related to its pro-oxidant activity." (PMID 35624738, 2022). "Inflammation goes hand in hand with the atherosclerotic process, which is important key event of endothelial damage.C-reactive protein (CRP), myoglobin (MYO), creatinine kinase myocardial band (CKMB), cardiac troponins, and myeloperoxidase aresalivary markers of cardiovascular diseases." (PMID 37693919, 2022). "After excluding those with thyroid-related diseases (n = 31), family history of cardiovascular disease (n = 285) and the those with lowest 1% or 2.5% of 25(OH)D levels respectively, the association between 25(OH)D and MPO did not change." (PMID 35983482, 2022). "MPO has a long history as a candidate gene in cardiovascular disease." (PMID 35504531, 2022). "However, uncontrolled MPO release exaggerates inflammation, oxidative stress and metabolic disorders, leading to cardiovascular diseases and tissue damage." (PMID 36404308, 2022). "MPO has been associated with various cardiovascular diseases, but the link to AF is not so well established." (PMID 35651726, 2022). "In patients with CKD a large US study has shown MPO to be independently associated with CKD progression but not with cardiovascular disease or death." (PMID 35042473, 2022). "Serum amyloid A protein (SAA), neopterin (NP), myeloperoxidase (MPO), anti-apolipoprotein A-1 IgG (anti-apoA-1), and anti-phosphorylcholine IgM (anti-PC IgM) have been recently investigated in the same context and/or in cardiovascular diseases." (PMID 35011845, 2021). "The over-whelming data on adverse effects of MPO in cardiovascular disease with respect to only few described beneficial functions raise the question of whether the physiological properties of the enzyme have been adequately explored and described." (PMID 33916434, 2021). "Long‐term elevation of myeloperoxidase activity may be involved in the development of cardiovascular disease in humans." (PMID 30618054, 2019). "Interestingly, a few studies have indicated that salivary levels of MMP-9 and MPO are potentially promising biomarkers in cardiovascular disease." (PMID 30726210, 2019). "Saliva has emerged as a non-invasive tool for assessing MMP-9 and MPO in cardiovascular diseases." (PMID 30726210, 2019). "We hypothesise that circulating pro-MPO can contribute to oxidative cell damage such as that previously attributed to mature MPO in cardiovascular disease." (PMID 29590135, 2018). "We hypothesized that in addition to circulating MPO, catalytically active pro-MPO can contribute to oxidative modifications of proteins leading to cardiovascular disease." (PMID 29590135, 2018). "Monomeric pro-myeloperoxidase (pro-MPO) is a catalytically active precursor of MPO, but whether it is present in human plasma and whether it contributes to cardiovascular disease is unknown." (PMID 29590135, 2018). "Since MPO and MPO-derived oxidants promote inflammation and cause tissue damage, the neutrophil to lymphocyte ratio (NLR) has become a good predictor of poor prognosis and mortality of many cardiovascular diseases." (PMID 29868513, 2018). "While MPO-derived oxidants play a key role in the innate immune-response by facilitating microbial killing, they have also emerged as a contributor to progressive tissue damage during chronic inflammation, i.e. in cardiovascular disease." (PMID 29590135, 2018). "In conclusion, intracellular monocyte myeloperoxidase was not evidently associated with incident cardiovascular disease in this prospective population-based study." (PMID 30300402, 2018).